SIRT2 (sirtuin 2)
Diseases named in the same sentence as SIRT2 in open-access papers (continued):
Sharing a sentence is not in itself a finding about the gene and the disease.
cancer (continued). "In addition to tumor suppression, knockdown of SIRT2 or pharmacological inhibition provides an antiproliferative effect in cancers." (PMID 28197299, 2017). "Decreased SIRT2 correlates with higher grade cancer (p = 0.02)." (PMID 29262808, 2017). "SIRT2 overexpression suppresses cell proliferation and induces apoptosis in cancer cells." (PMID 28061480, 2017). "Moreover, this is the first study exploring the prognostic value of the simultaneous expression of SIRT1 and SIRT2 in the same cancer patient." (PMID 25915617, 2015). "There are many indications that sirtuins play an important role in neurodegeneration, cancer, bacterial infections and inflammation and that a modulation of Sirt2 activity could be a new strategy for pharmaceutical intervention." (PMID 25672491, 2015). "In addition, the FOXO1 transcription factor has been shown to dissociate from SIRT2 in human cancer cells in response to oxidative stress or starvation." (PMID 25486244, 2014). "Therefore, we propose that targeting SIRT2, a protein thought to function as a tumor suppressor in cancer cells, is a viable strategy for inducing leukemic cell differentiation." (PMID 23460888, 2013). "Similarly, another SIRT2 inhibitor, compound AC-93253 showed selectively decreasing viability in several human cancer cell lines over their human primary cells controls." (PMID 24259290, 2013). "Therefore, the development of potent and selective Sirt2 inhibitors provides an important contribution to understanding physiological and pathophysiological mechanisms, particularly for the research and treatment of cancer and neurodegenerative diseases." (PMID 40333696, 2025). "However, SIRT2 can also promote tumorigenesis by supporting cancer cell proliferation and survival." (PMID 40710366, 2025). "Studies have suggested that SIRT2 may be a novel target for cancer treatment." (PMID 38216561, 2024). "SIRT2 expression may vary significantly in various types of cancers, much like SIRT1." (PMID 37175631, 2023). "SIRT2 may inhibit cancer cells from producing VEGF, CTGF, and ATP citrate lyase (ACLY)." (PMID 37175631, 2023). "Similarly to SIRT2, HDAC6 is also associated with tumorigenesis and metastasis, and the inhibition of this enzyme is an interesting approach to treating several types of cancer." (PMID 37106761, 2023). "Additionally, SIRT2 is involved in the activation of genes associated with epithelial-mesenchymal transition (EMT), which reduces intercellular adhesion, fostering aberrant cancer cell proliferation and migration." (PMID 36750593, 2023). "Thus, aberrant SIRT2 secretion from macrophages contributes significantly to cancer metastasis." (PMID 36453571, 2023). "Thus SIRT2-activating molecules may be used to downregulate FOXM1 to diminish the proliferative potential of cancer cells." (PMID 35326523, 2022). "Thus, inhibition of SIRT2 may have broad anticancer effects in a variety of human cancer cells and mouse breast cancer models." (PMID 36712965, 2022). "Likewise, SIRT2 may influence sensitivity to chemotherapeutics positively or negatively, depending on the cancer type." (PMID 33800266, 2021). "Furthermore, SIRT2 can inhibit proliferation and colony-formation capacity of cancer cells." (PMID 33921908, 2021). "Interestingly, a negligible effect of TM action is observed both in non-tumor cells and in tumor-free mice, indicating a greater dependence of cancer cells on SIRT2, which may indicate SIRT2 as a potential therapeutic target." (PMID 34769241, 2021). "However, the role of SIRT2 in the immune response to cancer remains largely elusive." (PMID 33061819, 2020).
cancer (continued). "Additionally, cancer subtypes should be fully considered as SIRT2 might have distinct functions in different oncopathological conditions." (PMID 33014852, 2020). "In addition, multiple cancer-associated mutations have been identified in SIRT2, however none have yet been demonstrated to affect its localisation." (PMID 32042025, 2020). "Indeed, previous studies have reported the disorder of SIRT2 in various types of cancers, suggesting that SIRT2 might suppress tumorigenesis via multiple mechanisms." (PMID 33061819, 2020). "Since disruption of Sirt2 by siRNA or Sirt2 inhibitor AGK2 suppressed dNTP synthesis leading to cancer cell growth inhibition, pharmacological control of RRM2 acetylation by targeting its upstream deacetylase may represent a novel and effective approach for cancer therapy." (PMID 31324785, 2019). "Therefore, selective inhibitors of SIRT2 are candidate therapeutic agents for cancer." (PMID 30081901, 2018). "Thus, SIRT2 inhibitors are promising lead candidates for use in cancer treatments." (PMID 30081901, 2018). "Furthermore, SIRT2 expression is down-regulated in some cancers, suggesting that SIRT2 may be a tumor-suppressor." (PMID 26942878, 2016). "Furthermore, other sirtuins might play important roles in some diseases, as illustrated by SIRT2, which could be involved in the treatment of both cancer and PD." (PMID 27713233, 2009). "Co-expressed genes of SIRT2 in tumor tissues were found to be enriched for pathways related to metastasis and EMT, a key process in cancer progression." (PMID 41471349, 2025). "In particular, inhibitors specifically designed to interfere SIRT2-GCLC association and subsequent GCLC activation may be utilized to enhance tumor treatment efficacy while decreasing the toxicity to normal cells, which has the potential to ultimately improve the prognosis of cancer patients." (PMID 40188196, 2025). "Our findings are the first to demonstrate that GCLC desuccinylation mediated by SIRT2 directly regulates the rapid activation of GCLC upon oxidative stress, which provides a promising adjunct therapeutic target for cancer treatment." (PMID 40188196, 2025). "Through identifying SIRT2 as the desuccinylase of GCLC, their corroborative roles in coping with the excessive oxidative stress-induced ferroptosis in cancer cells were further determined." (PMID 40188196, 2025). "m6A modification by METTL3 stabilizes FBXO31 mRNA by binding to YTHDF1, which increases FBXO31 expression and promotes proteasome‐dependent degradation of sirtuin 2 (SIRT2), leading to cancer progression." (PMID 40448344, 2025). "Overall, these findings show that there are many ways NK cell activity is reduced in cancer, influenced by epigenetic enzymes like SIRTs (SIRT1, SIRT2, SIRT6), surface regulators like CD38, and signaling pathways like TGFβ-SMAD4." (PMID 41425553, 2025). "SIRT2 and HDAC3 can also mediate the deacetylation of FOXO1, inhibiting FOXO1 activity and autophagy and thereby promoting cancer progression." (PMID 39778006, 2025). "By contrast, associations of dasatinib sensitivity with stronger upregulation of SIRT1, SIRT2, and SIRT5 were unexpected, since these genes have tumour promoting effects, and their downregulation positively affects cancer treatment outcomes." (PMID 38369747, 2024). "The recommended Sirt2 inhibitors TM, AF8/AF10, and SirReal2 display nanomolar potency, high isoform selectivity, and efficacy in various cancer models." (PMID 38474697, 2024). "SIRT2 is also capable of altering APC/C acetylation levels, and using this mechanism, SIRT2 knocks out some of the cancer formations in mice." (PMID 37175631, 2023). "PADI3 can affect the proliferation and invasion of tumor cells by regulating energy metabolism, EV and signal transduction (Sirt2/p21/AKT/Snail, Hsp90/CKS1), thereby inhibiting or promoting cancer." (PMID 37020554, 2023).
cancer (continued). "We identified four proteins (p21, NFkB1, MAPK1, and Sirt2) as potential target gene candidates regulated by SRSF3 through cell stress array analysis, correlation analysis, and expression levels between cancer and normal tissues." (PMID 36344491, 2022). "The top-ranked compounds were docked in the apo form of SIRT-2 (PDB code 1J8F) and four candidates were evaluated in vitro (the best inhibitors, namely, 8c and (R)-8c, showed potent anti-cancer effects, see Section 2.2.1)." (PMID 36080416, 2022). "SIRT2, an NAD-dependent histone deacetylase, has been suggested to be a promising therapeutic target in cancer treatment." (PMID 35845599, 2022). "In this regard, the group developed a SIRT2 inhibitor, JH-T4, a small molecule that successfully modulates the lysine fatty acylation levels of KRAS4A and was cytotoxic to several human cancer cells." (PMID 36393833, 2022). "HDAC1 was shown to be one of the oncogenes deleted in the 1p deletion event, and SIRT2 and EP300 were two cancer suppressors lost in 19q deletion and 22q deletion events, respectively." (PMID 33718432, 2021). "Therefore, it could be advantageous to use SIRT2-selective inhibitors to treat cancers." (PMID 34650436, 2021). "SIRT2 deacetylates and activates LDH-A, which is responsible for lactate production in cancer cell growth." (PMID 34650436, 2021). "A mechanism-based SIRT2 inhibitor, TM showed broad anticancer effect in most of the NCI-60 cancer cell lines." (PMID 34650436, 2021). "SIRT2, an NAD+-dependent histone deacetylase, has been shown to play a pivotal role in various physiological processes, however, its role in cancer is currently controversial." (PMID 34155309, 2021). "Sirtuin 2 (SIRT2), a member of class III NAD+ dependent histone deacetylases (HDACs), has been reported to be involved in regulating cancer hallmarks including drug response." (PMID 33207824, 2020). "On the contrary, higher level of HDACs such as SIRT1, SIRT2, and SIRT7 were detected in cancer cells." (PMID 33262941, 2020). "However, there are examples where SIRT2 acts as an oncogene and may target various cancers." (PMID 32697380, 2020). "Genetic ablation as well as pharmacological inhibition of sirtuin 2 (SIRT2), an NAD+-dependent protein deacylase, have therapeutic effects in various cancers and neurodegenerative diseases." (PMID 31973227, 2020). "An earlier study suggests that SIRT2-mediated deacetylation promotes FOXO3 transactivation activity to reduce cellular ROS and induce cell death in cancer cells." (PMID 32372224, 2020). "Notably, in human cancers, whether SIRT2 is an oncogene or a tumour suppressor are debated." (PMID 32697380, 2020). "As noted, SIRT2 deacetylates the transcription factor FOXO1, which regulates autophagy in human cancer cell lines in response to oxidative stress or serum starvation." (PMID 31492861, 2019). "The activity of SIRT2 enhances N-MYC and c-MYC protein stability, promoting cancer cell proliferation." (PMID 30761005, 2019). "In cancer cells, in response to oxidative stress or serum-starvation, FOXO1 can be acetylated by Sirtuin-2 (Sirt-2), where the acetylated FOXO1 can bind to Atg-7 thereby mediating transcription-independent autophagy and promoting tumour suppression." (PMID 29180117, 2018). "Nevertheless, several reports have demonstrated that the knockdown of SIRT1, SIRT2, or SIRT1/2 genes affected less cancer cell viability but essentially proliferation and/or invasion." (PMID 29401749, 2018). "SIRT2 activates lactate dehydrogenase A (LDH-A) and the increased amount of LDH-A was noted in many cancer cells." (PMID 28197299, 2017). "In fact, recent studies show that Sirt2 affects the activity of phosphoglycerate mutase (PGAM), a glycolytic enzyme, preventing the Warburg effect in cancer cells." (PMID 26135889, 2015).
cancer (continued). "Perhaps by combining current frontline therapies, with inhibitors of SIRT1 or SIRT2, along with a FZD7 antagonist, we can create a synergistic effect in cancers with an over-active Wnt pathway." (PMID 24897117, 2014). "SIRT2 is specifically expressed in GSCs but not in normal neural stem cells, suggesting a unique function in cancer stem cell biology." (PMID 40710366, 2025). "HDAC6 and SIRT2 can also deacetylate KRAS at lysine 104 and promote cancer cell growth." (PMID 39778006, 2025). "SIRT3 exhibits context-dependent roles in cancer, similar to SIRT1 and SIRT2." (PMID 41304967, 2025). "Drugs targeting SIRT2 and FLT4 were mainly designed to treat cancers." (PMID 38614964, 2024). "In addition, SIRT2 participates in the deacetylation of LDH, increases its activity, thereby contributing to the accumulation of lactic acid and proliferation of cancer cells." (PMID 37175631, 2023). "SIRT2 is a member of NAD+-dependent sirtuins and its inhibition has been proposed as a promising therapeutic approach for treating human diseases, including neurodegenerative diseases, cancer, and infections." (PMID 38005376, 2023). "Notably, the mRNA levels of SIRT2 are elevated in HCC and several other cancers compared with levels in normal tissues according to The Cancer Genome Atlas (TCGA) data." (PMID 37115693, 2023). "Although the exact effect of SIRT2 in cancer development is still under debate, our study supports the role of secreted SIRT2 in promoting cancer cell detachment and migration, rather than growth." (PMID 36453571, 2023). "The conditioned medium of wild type SIRT2 significantly increased cancer cell invasion and metastasis properties without affecting the proliferation property in A549 cells." (PMID 36453571, 2023). "This could be due to the activation of a response by cancer cells, like THP-1, which counteracted SIRT2 down-regulation mediated by BJe, by restoring its mRNA at the level of untreated cells." (PMID 36297603, 2022). "In addition, Sirtuin 2 (Sirt2) maintains cellular iron concentrations through the deacetylation of NRF2, which results in decreased FPN1 expression in cancer cells and in a mouse model." (PMID 33714956, 2021). "SIRT2 and SIRT5 inhibitors showed rather consistent and promising effect in treating cancers." (PMID 34650436, 2021). "In human cancers, it is presently unclear whether increased SIRT1 or SIRT2 expression irritates or obstructs the forming and/or preservation of malignancy." (PMID 33705642, 2021). "Owing to its regulatory roles in various cellular processes, perhaps it is not surprising that the dual roles of SIRT2 as a cancer suppressor as well as an oncogene have been reported." (PMID 31973227, 2020). "In support of Sirt2’s tumor-promoting function, here we discovered that Sirt2 deacetylates RRM2 to enhance RNR activity leading to increased dNTPs pool size and proliferation of cancer cells." (PMID 31324785, 2019). "Given the different functions regulated by SIRT2 and SIRT3, unraveling downstream targets/pathways involved may provide opportunities to develop new strategies for cancer prevention." (PMID 31970087, 2019). "Unfortunately, to our knowledge, there are no known SIRT2 or other SIRT inhibitors undergoing clinical evaluation for the treatment of cancer to date." (PMID 31091806, 2019). "This evidence prompted us to ask whether SIRT2 regulates tumour angiogenesis in CRC, which is one of the most common cancers worldwide." (PMID 30584257, 2018). "Other specific sirtuin inhibitors (SIRTi) have been reported to trigger cancer cell death, including the SIRT1 inhibitors NCO-01 and -04, and the SIRT2 inhibitors AEM1 and AEM2, which induce cell death in T-cell leukemia/lymphoma and in non-small cell lung cancer, respectively." (PMID 29401749, 2018). "In tissues, nuclear SIRT2 staining shows a decline from benign to malignant and metastasis (p = 0.04 and 0.03 respectively), but not between cancer and metastatic groups (p = 0.18)." (PMID 29262808, 2017).
cancer (continued). "Sirtuin 2 (SIRT2), a member of the NAD+-dependent histone deacetylase family, has recently received increasing attention due to its potential involvement in neurodegenerative diseases and the progression of cancer." (PMID 28989670, 2017). "By contrast, SIRT2 has negative implications in certain types of cancer including acute myeloid leukemia, pancreatic cancer, neuroblastoma, high-grade human HCC and prostate cancer." (PMID 27916001, 2016). "Salermide and Sirtinol inhibit Sirt1 and Sirt2 and they induce apoptosis in cancer cell lines, but not normal cell lines." (PMID 24069483, 2013). "Concerning the experiments in cancer cells, the correlation between SIRT1 inhibition and the reported effects should be interpreted cautiously, since the doses employed (e.g., 50 μM or even more) in some studies may have also determined SIRT2 inhibition." (PMID 39215785, 2025). "Functionally, we demonstrated that the silencing of SIX1, SIRT2 and CDKN2A expression could accelerate the migratory and invasive capacities of tumor cells, whereas the downregulation of PGR dramatically inhibited cancer cells migration and invasion." (PMID 37723477, 2023). "Notably, as HSP70 inhibition is known to be advantageous for the development of anti-cancer agents, the identification of dual inhibitors (against HSP70 and SIRT2) may represent a promising strategy for contrasting tumors." (PMID 37765125, 2023). "Importantly, we demonstrate that NAD+ mediates SIRT2-dependent neuroprotection without inhibiting cisplatin cytotoxic activity against cancer cells." (PMID 35875690, 2022). "Finally, we provide data that show pharmacological activation of SIRT2 protects neuronal cells against cisplatin-induced cytotoxicity without compromising cancer cell sensitivity." (PMID 35875690, 2022). "Under conditions of nutrient excess, the activity of SIRT2 decreases, and the level of the acetylation of PKM2 increases, which increases its enzymatic activity and decreases lactate production and pyruvate accumulation, thereby resulting in a similar Warburg effect to promote cancer progression." (PMID 36101744, 2022). "The tumor suppressive effect of DCA or Nic combination regimens has been demonstrated in xenografts of different cancer types: DCA/activated natural killer cells/anti-CD20, DCA/4‐methylumbelliferone, DCA/arginase, DCA/sirtinol (SIRT2 inhibitor), DCA/cisplatin, Nic/cisplatin and Nic/paclitaxel." (PMID 36304150, 2022). "In addition, it has been suggested that the absence of SIRT2 promotes genomic instability, a recognized early event in the development of cancer (7, 53, –, 55)." (PMID 31932479, 2020). "Therefore, SIRT2 activation upon CR and SIRT3 inhibition upon HFD could be explored as new strategies to enhance CR-induced cancer prevention and decrease HFD-induced tumor development, respectively." (PMID 31970087, 2019). "SIRT2 also directs other physiological processes, including gluconeogenesis, insulin sensitivity, and fatty acid oxidation, and is critical for insulin-dependent AKT activation, suggesting that the inhibition of SIRT2 may have an impact on cancer growth." (PMID 30405152, 2018). "Two sirtuins of interest for targeted cancer therapy include SIRT1 and SIRT2, which deacetylate histones H3, H4, and nonhistone substrates, playing a key role in DNA repair and oxidative stress mitigation." (PMID 41333420, 2025). "Nevertheless, in some other cancers, it was shown that SIRT-2 possesses tumor suppressor functions, which, however, were not further investigated pharmacologically, since no SIRT-2 activators are currently available." (PMID 36080416, 2022). "In conclusion, accumulated evidence demonstrates pharmacological SIRT2 activation with NR effectively protects differentiated DRG neurons, but not proliferating cancer cells, from DNA damage-induced cytotoxicity from cisplatin." (PMID 35875690, 2022).